BDNF (brain derived neurotrophic factor)
Diseases named in the same sentence as BDNF in open-access papers (continued):
Sharing a sentence is not in itself a finding about the gene and the disease.
Obesity (continued). "Moreover, our finding that BDNF levels do not differ between patients suffering from obesity and normal-weight participants mirrors some but not all previous studies showing either higher BDNF levels or lower levels in patients suffering from obesity, if compared to normal-weight participants." (PMID 33367955, 2021). "In addition, overweight/obesity probably result in lower BDNF levels, which might lead to a lack of neurotrophic support in the adult brain and cause dysfunction of the hippocampus, presumably impairing performance of EC." (PMID 33916706, 2021). "As the results of gene enrichment pathways analysis exhibited that TAPBP, BDNF, and SRBP2 are related together by inflammatory pathways, we hypothesis that hypermethylation in these genes might play a crucial role in the co-occurrence of obesity and mood disorders due to the inflammation process." (PMID 32942585, 2020). "The two markers of cerebral plasticity (BDNF and S100B) were not significant predictors of the behavior in our participants, corroborating our hypothesis about the relationship between inflammatory state and poorer temporal sensitivity in obesity." (PMID 31664059, 2019). "In the current study, we did not observe any relationships between adiposity and BDNF levels, which is consistent with a recent sample of 447 healthy adolescents, whereas other studies have reported BDNF levels that are both lower or higher in youth with obesity compared to those without." (PMID 30363954, 2018). "Exercise suppresses appetite through modulators such as lactate, BDNF, sex hormones, growth differentiation factor 15 (GDF15), and asprosin, but is not closely related to GLP-1 in individuals with obesity." (PMID 40426650, 2025). "In contrast to the adverse effects of visceral adipose tissue in aged humans and animals and those with obesity, the tissues in young and non-obese mice express CX3CL1 to signal to the hippocampus, thereby maintaining the BDNF protein level." (PMID 40724847, 2025). "However, whether obesity itself may influence circulating BDNF levels is not well-defined as yet." (PMID 35911513, 2022). "To conclude, BDNF concentrations of children with obesity with and without OSA are comparable in our cohort, suggesting that BDNF levels are not affected by OSA." (PMID 35127775, 2021). "Although studies suggest that MC4R signaling interacts with BDNF-TrkB signaling in the context of body weight regulation, it is unlikely that Ntrk2 deletion in the PVH leads to obesity through the MC4R because the deletion did not reduce levels of Mc4r mRNA." (PMID 32265438, 2020). "Two-way ANOVA showed a main effect of maternal HFD/obesity treatment (p < 0.01), but not postnatal HFD on hippocampal BDNF level." (PMID 32408716, 2020). "In conclusion, diabetic patients with obesity had higher FGF21 and similar BDNF levels compared to non-diabetic obese patients." (PMID 32210348, 2020). "Similarly, 3 weeks of intermittent BDNF administration significantly reduced blood glucose concentrations and glycated hemoglobin (HbA1c) in db/db mice model, which are defined by nonfunctional leptin receptor and provide a model for obesity and non-insulin-dependent T2DM." (PMID 29062839, 2017). "To investigate the feasibility of trkB agonism as a therapeutic approach for human obesity, we conducted a series of experiments using NT4, BDNF and TrkB agonistic antibody in several species of non-human primates." (PMID 18382675, 2008). "Other studies have suggested that obesity increases adipose CX3CL1 expression; however, CX3CL1 augmented under obese condition may not contribute to the promotion of the BDNF level in the hippocampus." (PMID 40724847, 2025). "Notably, mice lacking one copy of Rai1 in the BDNF-producing cells do not exhibit obesity, whereas SMS patients and SMS mice show pronounced obesity." (PMID 37956053, 2023).
Obesity (continued). "Other signals such as EGF, BDNF, FGF, other growth factor signals, autonomic neuronal signals, myokines, muscle damage, pain and infection have been shown to affect insulin sensitivity partly or completely independent of obesity." (PMID 33544739, 2021). "Unger and collaborators demonstrated that glucose administration in adult mice induced an increase in both BDNF and TrkB levels in VMH and that the deletion of the BDNF gene in the VMH and DMH produced hyperphagic obesity without changing energy output and locomotion." (PMID 34833132, 2021). "Interestingly, although BDNF is required in the VMH and DMH to regulate body weight, embryonic deletion of Bdnf from the SF1-lineage populations including the VMH did not result in obesity." (PMID 37956053, 2023).
cognitive decline (439 papers, 2009 to 2026). "In accordance with its pro-synaptic functions, BDNF mRNA and BDNF protein levels are significantly reduced in the hippocampus and associative cortex of AD patients, corresponding to synapse loss and cognitive decline." (PMID 41009553, 2025). "The connection between serum BDNF and AD progression has been associated with the pace of cognitive decline." (PMID 40709526, 2025). "This polymorphism has been linked to reduced BDNF secretion and increased risk of cognitive decline, particularly in women." (PMID 40864734, 2025). "Reduced BDNF levels are associated with cognitive decline in neurodegenerative diseases, and by regulating BDNF, PGC-1α helps preserve synaptic function and cognitive health." (PMID 40926269, 2025). "An interesting study demonstrated the association between serum BDNF levels and cognitive decline observed in a group of patients who had previously had mild COVID-19." (PMID 40709999, 2025). "Clinically, higher serum vitamin D levels have been associated with slower cognitive decline, potentially through upregulation of neurotrophic factors such as brain-derived neurotrophic factor (BDNF) and enhancement of acetylcholine synthesis." (PMID 40551736, 2025). "Cognitive decline is associated with reduced synaptic plasticity, as measured by peripheral markers such as brain-derived neurotrophic factor (BDNF), nerve growth factor, neurogranin, and synaptophysin." (PMID 40724948, 2025). "This age-related reduction in BDNF, coupled with diminished neurotrophic support, is associated with cognitive decline, increased neurodegenerative risk, and muscle weakness, all hallmarks of aging [1069–1071]." (PMID 40407975, 2025). "Reduced NE turnover has also been linked to cognitive decline in stress and hypoxia studies with NE concentration regulating BDNF and NGF expression." (PMID 40546247, 2025). "Our findings firmly establish this phenomenon within an older adult cohort, a population uniquely vulnerable to both the causes (e.g., physical frailty) and consequences (e.g., cognitive decline) of reduced BDNF." (PMID 41164095, 2025). "Reduced BDNF has been tied to hippocampal atrophy, cognitive decline, and a greater risk of mood disorders." (PMID 40871678, 2025). "The GH/IGF-1 system is involved in promoting longevity and regulating metabolism, while BDNF is associated with cognitive decline in patients who have had COVID-19." (PMID 40709999, 2025). "Serum BDNF levels were associated with the rate of cognitive decline in AD, and serum proBDNF levels were associated with hippocampal proBDNF levels, which were associated with hippocampal pTau expression." (PMID 40649882, 2025). "Cognitive decline associated with synapse loss, retraction of dendritic arbors, and deficits in learning/memory underscores the importance of BDNF signaling in driving and maintaining neural networks." (PMID 40362507, 2025). "It induces BDNF production, alleviating memory impairment associated with cognitive decline and promoting antioxidant genes for cognitive enhancement." (PMID 40807615, 2025). "Concurrently, BDNF increases the plasticity of the cortical dendritic spines, and synaptic loss is considered an accurate indicator of cognitive decline in AD." (PMID 40278547, 2025). "Studies have consistently shown that exercise-induced increases in BDNF are associated with improvements in both short-term and long-term memory, helping counteract the cognitive decline that accompanies aging." (PMID 40001727, 2025). "A recent systematic review suggested a significant association between decreased serum BDNF levels and cognitive decline in PD." (PMID 41425070, 2025). "Further longitudinal studies are required to explore the association of BDNF Val66Met polymorphisms with CI or other forms of cognitive decline of various etiologies to confirm our findings." (PMID 38374884, 2024).
cognitive decline (continued). "LH and BDNF, importantly, are known to participate in cognitive decline through loss of memory most likely associated with the hippocampus." (PMID 39014006, 2024). "Cognitive decline has been associated with a decrease in brain-derived neurotrophic factor (BDNF) levels." (PMID 39931196, 2024). "Mediation modeling showed that BDNF levels attenuated the association between platelet hyperactivity and cognitive decline, with BDNF having a weaker protective effect on cognitive function in participants with CAD than in controls." (PMID 39568824, 2024). "BDNF supports various neuron types, including cholinergic and dopaminergic neurons, and its depletion has been linked to cognitive decline and motor dysfunction." (PMID 39474368, 2024). "Interesting research demonstrated an association between serum BDNF levels and cognitive decline observed in a group of patients who previously experienced mild COVID-19 disease." (PMID 39596862, 2024). "The authors showed that decreased serum levels of BDNF are associated with cognitive decline in patients undergoing CABG surgery." (PMID 38672112, 2024). "There are reports that exercise can improve cognitive decline caused by neurodegenerative diseases through mechanisms such as promoting adult neurogenesis, generating brain‐derived neurotrophic factor, and metabolizing short‐chain fatty acids." (PMID 39155519, 2024). "By reducing inflammation in the brain, BDNF contributes to resilience against cognitive decline and neurodegeneration associated with aging." (PMID 39656488, 2024). "Low levels of BDNF, both in peripheral blood and in cerebrospinal fluid, were associated with cognitive decline." (PMID 39555041, 2024). "BDNF is associated with AD-related pathology, including neuroinflammation, neuronal apoptosis, and cognitive decline." (PMID 39139674, 2024). "The standardized regression coefficient (β) for the association between BDNF and cognitive decline (b) was 1 (P < 0.05)." (PMID 38559694, 2024). "BDNF, an additional gene implicated in AD, is linked to cognitive decline, particularly in immediate memory." (PMID 37790702, 2023). "This association between reduced BDNF and the higher risk of cognitive decline was still evident at 24 months post-treatment." (PMID 36720792, 2023). "In the past 10 years, the role of BDNF-Val66Met (BDNF-Met) polymorphism in the progression of cognitive decline in both sporadic and familial AD has been well described." (PMID 37446337, 2023). "One possible mechanism for this effect is the increase in brain-derived neurotrophic factor (BDNF) associated with exercise, as higher expression levels of BDNF correlate with slower cognitive decline." (PMID 37065695, 2023). "Future studies should include COMT genotypes as a potential interaction in polygenetic risk scores with other genes thought to impact aging (e.g., BDNF) including a more diverse sample and should use such variables to predict cognitive decline over time." (PMID 37744392, 2023). "In order to assess the association of plasma BDNF concentrations and cognitive decline in subjects with MCI and patients diagnosed with AD, Spearman’s correlation coefficient was used." (PMID 36979505, 2023). "As expected, an alteration of the BDNF/TrkB system is suspected to be one of the molecular mechanisms underlying cognitive decline in cognitive diseases and mental disorders." (PMID 37781095, 2023). "Lower BDNF levels have been associated with quicker cognitive decline, poor memory performance, and learning difficulties in AD, as well as other behavioral disturbances in the AD group." (PMID 37631278, 2023). "This study shows an association between vitamin D on serum BDNF and vitamin D on cognitive decline in older adults." (PMID 36629701, 2023). "Brain-Derived Neurotropic Factor (BDNF) expression is decreased in conditions associated with cognitive decline as well as metabolic diseases." (PMID 36138878, 2022).
cognitive decline (continued). "As shown by a number of studies described in this article, a weakened BDNF/TrkB signaling is a common downstream pathology in cognitive decline associated with normal aging and age-related diseases." (PMID 35887075, 2022). "Further support comes from studies showing that the BDNF Val66Met polymorphism decreases the hippocampal–medial prefrontal connectivity, increases the vulnerability of the memory network to Aβ, and worsens cognitive decline." (PMID 35090576, 2022). "The association between serum BDNF and AD progression has been linked to the rate of cognitive decline." (PMID 35090576, 2022). "A recent study suggested that an imbalance in precursor and mature BDNF causes cognitive decline in POCD mice, which is consistent with the findings in the current study." (PMID 36212697, 2022). "This observational, prospective study documented associations between higher serum BDNF levels with decreased odds of cognitive decline 2 years later in community-dwelling older adults." (PMID 34239422, 2021). "The two modalities of cognitive decline caused by low concentrations of ZPR1 are reduced brain-derived growth factor (BDNF) synthesis and neuron death, both occurring in the hippocampus." (PMID 34746842, 2021). "Although the association between cognitive decline and reduction in blood BDNF levels has been reported, it has also been shown to decrease in AD and MCI." (PMID 33967943, 2021). "Our data demonstrate that serum BDNF is associated with cognitive decline and the development of AD dementia." (PMID 33661922, 2021). "In agreement, BDNF reduction has been largely linked to cognitive decline in AD patients and preclinical in vivo models, where its administration proved to be neuro- and synapto-protective." (PMID 33923297, 2021). "The results from this study showed that the presence of one or two T alleles of the BDNF rs56164415 was related to cognitive decline in PTSD." (PMID 33926045, 2021). "In veterans with PTSD who smoked, BDNF rs56164415 was associated with cognitive decline in smokers in the genotype (H = 10.729; df = 2; p = 0.005), dominant (U = 9327.0; p = 0.003), and allelic (U = 24113.5; p = 0.011) model." (PMID 33926045, 2021). "Our findings recapitulate the outcomes of this previous study and demonstrate that serum BDNF, assessed when subjects were cognitively normal, is associated with cognitive decline during 10 years after sample collection." (PMID 33661922, 2021). "The expression of BDNF is tightly regulated and alterations in BDNF levels and function have been suggested to underlie both the cognitive decline during aging processes as well as the pathogenesis of several neurological and psychiatric disorders." (PMID 32349283, 2020). "The synaptic loss and cognitive decline observed in AD is often associated with reductions of synaptic proteins and BDNF, one of the major neurotrophins regulating neuronal survival and synaptic plasticity." (PMID 32933545, 2020). "Increased BDNF serum levels are associated with reduced cognitive decline, while BDNF therapy results in increased synaptic efficiency and plasticity and increased neuronal survival." (PMID 32719583, 2020). "In particular, brain-derived neurotrophic factor (BDNF) plays a fundamental role during age-related synaptic loss, preventing cerebral atrophy and cognitive decline." (PMID 32397504, 2020). "High amyloid-beta load in the brains of cognitively normal older BDNF Met carriers, relative to Val homozygotes, has been linked with worse episodic memory and executive function and with a steeper trajectory of cognitive decline over time." (PMID 32218234, 2020). "Loss of BDNF in neurodegenerative disorders is a key mediator of synaptic dysfunction, neurodegeneration and subsequent cognitive decline." (PMID 31293498, 2019). "Decreased levels of BDNF have been associated with cognitive decline in aging individuals physically active in specific components of memory, but not in those of EF." (PMID 28469588, 2017).